GATA2 (GATA binding protein 2)
Diseases named in the same sentence as GATA2 in open-access papers (continued):
Sharing a sentence is not in itself a finding about the gene and the disease.
atherosclerosis (7 papers, 2020 to 2025). A disease characterized by the build-up of fatty material and calcium deposition in the arterial wall resulting in partial or complete occlusion of the arterial lumen. "Previous research has shown that GATA2 can promote the progression of atherosclerosis by upregulating NRP2." (PMID 40963808, 2025). "Among major findings, our results suggest a role of triglyceride-associated and mast-cell functional genes FCER1A, MS4A2, GATA2, HDC, and HRH4 in atherosclerosis risks." (PMID 39276247, 2024). "SENP1 modulates the SUMOylation of GATA2 and leads to endothelial dysfunction in graft atherosclerosis." (PMID 36293488, 2022). "GATA2 was also modified to regulate the expression of endothelial cell adhesion molecules and jointly regulate the inflammatory progression of atherosclerosis." (PMID 35855865, 2022). "Our data implicates GATA2 as a driver of macrophage dysfunction in early human atherosclerosis and provides a detailed map of the transcriptional changes occurring in macrophages during the early stages of plaque formation." (PMID 33193444, 2020). "This transcriptional state was characterized by the high expression of the hematopoietic transcription factor GATA2, with GATA2 overexpression in vitro generating efferocytic defects similar to those reported in atherosclerosis." (PMID 33193444, 2020). "Meanwhile, phagocytic GATA2 overexpression drives atherosclerosis formation." (PMID 38685029, 2024). "However, neither GATA2 overexpression nor the GATA2 shRNA had any effect on cholesterol accumulation or export in these cells, indicating that GATA2 plays only a minor role in the perturbance of cholesterol homeostasis during atherosclerosis." (PMID 33193444, 2020). "Therefore, SUMO and SUMOylation play a crucial role in atherosclerosis, and SUMOylation of ERK5, SENP2, and GATA2 may be potential therapeutic targets for atherosclerosis." (PMID 35855865, 2022). "Several other TG-affected genes showed weaker associations with atherosclerosis-related outcomes (ABCG1, AC004791.2, CPA3, CYP11A1, SLC12A3) or rheumatoid arthritis (GATA2, SMPDL3A) but were no longer statistically significant after correction for multiple testing (PFDR > 0.05)." (PMID 36725846, 2023).
chronic myelomonocytic leukemia (7 papers, 2016 to 2025). A myelodysplastic/myeloproliferative neoplasm which is characterized by persistent monocytosis, absence of a Philadelphia chromosome and BCR/ABL fusion gene, fewer than 20 percent blasts in the bone marrow and blood, myelodysplasia, and absence of PDGFRA or PDGFRB rearrangement. "Presentation of GATA2 mutation in childhood is often related to myelodysplasia (MDS)/chronic myelomonocytic leukaemia (CMML), (particularly associated with monosomy 7), although prior or concurrent immunodeficiency features may be elicited [38▪▪]." (PMID 27755182, 2016).
dyskeratosis congenita (7 papers, 2017 to 2025). Dyskeratosis congenita (DC) is a rare ectodermal dysplasia that often presents with the classic triad of nail dysplasia, skin pigmentary changes, and oral leukoplakia associated with a high risk of bone marrow failure (BMF) and cancer. "SCID, CIDs, DiGeorge syndrome, Wiskott-Aldrich syndrome, Ataxia telangiectasia, Dyskeratosis congenita, ORAI-1 deficiency, CGD, X-linked Agammaglobulinemia, ALPS, STAT1 gain of function, CTLA-4 deficiency, GATA-2 deficiency, TRAPS, FMF, NEMO, TIM3, DOCK8, STAT2, STAT3, PIK3CD." (PMID 41049857, 2025).
myeloid leukemia (7 papers, 2017 to 2025). A clonal proliferation of myeloid cells and their precursors in the bone marrow, peripheral blood, and spleen. "An NGS study of 34 myeloid leukemia-associated genes was performed to assess the mutational profile of GATA2 in adult de novo CN-AML patients." (PMID 38416121, 2024). "MECOM isoform EVI1 has been reported to directly regulate gene transcription of MS4A3 in myeloid leukemia and of GATA2, regulating hematopoietic stem cell proliferation." (PMID 40664642, 2025). "High GATA2 expression is a poor prognostic marker in pediatric myeloid leukemia." (PMID 29029492, 2017).
Opportunistic infection (7 papers, 2019 to 2025). An infection that is caused by a pathogen that would generally not be able to cause an infection in a host with a normal immune system. "Pulmonary involvement is common in GATA2 deficiency, largely due to recurrent opportunistic infections caused by impaired monocyte/macrophage and dendritic cell function." (PMID 41438140, 2025). "The correlation between GATA2 mutations and opportunistic infections, along with other systemic complications, highlights the significant impact of GATA2-related disorders on patient health." (PMID 41154393, 2025). "Individuals with GATA2 mutations may suffer from severe opportunistic infections due to compromised immune responses, particularly impacting natural killer (NK) cells and other elements of the innate immune system." (PMID 41154393, 2025). "First, in terms of the distinction from GATA2 deficiency, although some of the clinical features such as PL and warts are shared, the overall clinical presentation, pattern of cellular abnormalities and occurrence of opportunistic infections are markedly dissimilar between the two syndromes." (PMID 34916230, 2023). "GATA2 deficiency, stemming from pathogenic variants in GATA2, is comprised of a syndrome characterized by life-threatening opportunistic infections with non-tuberculous mycobacteria (NTM), fungal infections, or human papillomavirus (HPV) infections and a propensity to progress to MDS, CMML, and AML." (PMID 37251919, 2023).
Alzheimer disease (6 papers, 2022 to 2025). A progressive, neurodegenerative disease characterized by loss of function and death of nerve cells in several areas of the brain leading to loss of cognitive function such as memory and language. "Among them, IL-7R + neutrophils was a superior cell group in Alzheimer’s disease, GATA2 deficiency with susceptibility to MDSAML, breast ductal adenocarcinoma, diffuse gastric adenocarcinoma, and retinoblastoma." (PMID 38319415, 2024). "Neuroglobin (NGB) gene expression is associated with neural disease (Alzheimer’s Disease) when the GATA2 TF works to regulate the NGB gene expression." (PMID 37993790, 2023). "Previous studies have connected GATA2 to rheumatism, and PRDM1 may be associated with Alzheimer’s disease development." (PMID 41007174, 2025). "In addition, network analysis identified GATA2 as an important transcription factor regulating transcriptomic changes in Alzheimer’s disease." (PMID 35370543, 2022). "In addition, network analysis identified important TFsFOXC1 and GATA2 regulating transcriptomic changes in Alzheimer’s disease and neurodegeneration." (PMID 36077049, 2022). "FOXC1, GATA2 and YY1 were found as regulatory TFs in several neurological conditions, such as Alzheimer's disease and various others." (PMID 39153206, 2024).
brain tumors (6 papers, 2020 to 2025). "GATA2, a zinc finger transcription factor traditionally associated with hematopoietic development, has recently emerged as an important regulator in various solid tumors, including brain tumors." (PMID 41154393, 2025). "Recent studies have established GATA2 involvement in brain tumor biology through multiple mechanisms." (PMID 41154393, 2025). "SOX6 and SOX13 could co-interact with FOXC1 and GATA2, which might lead to aggressive the brain tumors." (PMID 32388501, 2020). "Additionally, there was a significant positive correlation between expression of IGF2 and NFκB, GATA2 and STAT3 in brain tumor patients sampled in the CGGA dataset." (PMID 38853689, 2024).
colon cancer (6 papers, 2014 to 2024). "Moreover, the GATA2 gene has been identified as a prognostic factor in stromal-related studies of colon cancer, and it has also been implicated as a molecular signature in ovarian cancer through a network medicine perspective." (PMID 38166541, 2024). "Additionally, IL-1β activates miR-146a, which in turn targets p38, ERK, and JNK MAP kinases, along with downstream transcription factors GATA2, c-Fos, and c-Jun, that are implicated in metastatic progression in colon cancer cells." (PMID 38671854, 2024). "GATA2 gene has been identified in stroma-related studies in colon cancer prognosis, and also reported as a molecular signature in ovarian cancer via network medicine perspective." (PMID 33907495, 2021). "We also checked the effect of GATA2 silencing on focal adhesion disassembly since enhancement of this process is critically important for cell migration and has been shown to lead to metastasis in breast and colon cancer." (PMID 24448395, 2014).
fungal infections (6 papers, 2014 to 2023). "The MonoMac syndrome, also related to germline GATA2 deficiency, is characterized by dendritic cells, monocytes, and B/NK cell deficiencies, leading to the development of atypical mycobacterial or fungal infections, pulmonary alveolar proteinosis, and MDS/AML predisposition." (PMID 27248996, 2016).
glioma (6 papers, 2020 to 2025). A benign or malignant brain and spinal cord tumor that arises from glial cells (astrocytes, oligodendrocytes, ependymal cells). "We did not perform independent confirmation of the mutation using Sanger sequencing or assess its impact on GATA2 protein expression and function in glioma cells." (PMID 41154393, 2025). "This study identifies and evaluates a novel GATA2 p.Arg396Trp mutation in a clinical sample of lower-grade glioma, assessing its structural impact and implications for drug binding." (PMID 41154393, 2025). "This dual approach successfully identified promising therapeutic candidates targeting the mutated GATA2 protein in glioma." (PMID 41154393, 2025). "Through integrated genomic analysis, structural modeling, and drug affinity prediction, we aim to elucidate the potential pathogenic mechanisms of this novel GATA2 variant and its implications for therapeutic targeting in lower-grade gliomas." (PMID 41154393, 2025). "While our study provides a foundation for future investigations into the GATA2 role in glioma biology, the clinical significance of this mutation remains to be established through functional studies and expanded clinical series." (PMID 41154393, 2025). "The findings suggest that the p.Arg396Trp mutation in GATA2 likely has substantial implications for disease pathogenesis, necessitating further functional analysis to elucidate its role in gliomas." (PMID 41154393, 2025). "GATA2 has been directly implicated in promotion of glioma through the EGFR/ERK/Elk-1 pathway, further indicating its potential to forward tumor development in GBM." (PMID 32513296, 2020). "We report the first identification of a GATA2 p.Arg396Trp mutation in a lower-grade glioma patient." (PMID 41154393, 2025). "Moreover, GATA2 has been recognized as a crucial factor in the regulation of genes associated with brain stem cell biology, thereby underscoring its involvement in glioma pathogenesis." (PMID 41154393, 2025). "GATA2, a transcription factor crucial for hematopoietic and vascular development, has been implicated in various hematological malignancies and immune-related disorders but remains underexplored in glioma." (PMID 41154393, 2025). "Additionally, screening larger cohorts of lower-grade glioma patients for GATA2 mutations could establish the frequency and clinical significance of such alterations in this tumor type." (PMID 41154393, 2025). "This discovery highlights the potential of GATA2 as a novel candidate gene in glioma pathogenesis, warranting further investigation." (PMID 41154393, 2025). "GATA2, hematopoietic factor and gain of function assay revealed that GATA2 significantly enhanced proliferation, migration and invasion of glioma cells by activating EGFR signaling." (PMID 33643898, 2020). "The GATA2 p.Arg396Trp mutation was identified as a novel variant not previously reported in glioma literature." (PMID 41154393, 2025). "This research highlights the importance of genetic screening in lower-grade gliomas and suggests that GATA2 could be a potential biomarker for precision medicine approaches." (PMID 41154393, 2025). "The biological relevance of the GATA2 p.Arg396Trp mutation in glioma pathogenesis cannot be established without validation in larger patient cohorts." (PMID 41154393, 2025). "Furthermore, the correlation of GATA2 with additional oncogenic pathways in gliomas has been investigated." (PMID 41154393, 2025). "This interaction indicates that GATA2 may be integral to a wider network of regulatory elements that affect glioma biology and patient outcomes." (PMID 41154393, 2025). "A study also demonstrated that GATA2 overexpression led to increased proliferation of SW1783 glioma cells, whereas GATA2 knockdown notably inhibited the proliferation of U87 glioma cells." (PMID 39906820, 2025).
hemophagocytic lymphohistiocytosis (6 papers, 2021 to 2026). "In a particular case series, GATA2 deficiency was linked to severe primary EBV infections requiring hospitalization or hemophagocytic lymphohistiocytosis with lymphoma, indicating that this genetic deficiency might influence disease presentation in certain instances." (PMID 38543828, 2024).
non-small cell lung carcinoma (6 papers, 2014 to 2025). A group of at least three distinct histological types of lung cancer, including non-small cell squamous cell carcinoma, adenocarcinoma, and large cell carcinoma. "Similarly, loss of the transcription factor GATA-binding factor 2 (GATA2) reduces the viability of newly diagnosed non-small-cell lung cancer (NSCLC) cells harboring KRAS mutations, which drive aberrant KRas signaling." (PMID 40906088, 2025). "One study has demonstrated that GATA-2 is necessary for non-small cell lung cancer, via regulation of the proteasome, IL-1/NFκB signaling and Rho-signaling pathways, thereby providing enhanced proliferation for RAS-mutation." (PMID 24886974, 2014). "Similarly, GATA2 has also been suggested to be essential for non-small cell lung cancer malignancy driven by the RAS oncogene." (PMID 34592889, 2021). "GATA2 has a key role in hematopoietic development and the key to KRAS-driven non-small-cell lung cancer; its GC content (65.2%) is higher than the AT content (34.8%)." (PMID 34205890, 2021). "In KRAS mutant non-small cell lung cancer (NSCLC), GATA2 is involved in the regulation of the proteasome, IL-1-signaling, and Rho-signaling pathways." (PMID 26287967, 2015). "Tumor-associated neutrophils (TANs) display elevated PANoptosis gene expression and play pro-tumor activity with DCs via GATA-binding protein 2 (GATA2)-HMGB1-TIM-3 pathway, thereby hindering anti-tumor immunity and facilitating immune evasion of non-small cell lung cancer cells." (PMID 40721869, 2025).
ovarian carcinoma (6 papers, 2020 to 2024). A malignant neoplasm originating from the surface ovarian epithelium. "GATA2 expression was assessed by Western blotting and qRT-PCR in the ovarian cancer isogenic cell line pair, A2780 and A2780cis, and GATA3 expression in the isogenic PEO1 and PEO4 pair of cell lines, cultured in 0.5% hypoxia." (PMID 32850359, 2020). "CCLE analysis demonstrated that although the mRNA expression levels of GATA1 and GATA2 ranked the 14th and 16th highest in OC among different cancer cell types, the expression levels of GATA1 and GATA2 in ovarian cancer cells are generally low, (shown in green frame)." (PMID 35488350, 2022). "A recent paper revealed miRNA-124-3p targeting gene Gata2 might be a novel biomarker related to ovarian cancer progression based on multiomics analysis of the tumor microenvironment." (PMID 34539736, 2021). "Considering this, our study is consistent with a previous study that miR-124 might interact with target gene GATA2 to regulate the progression of ovarian cancer." (PMID 34539736, 2021). "RNA sequencing results revealed that disturbance of transcriptome was observed in shNTPCR ovarian cancer cells, and several miRNAs and TFs were predicted to be hub genes correlated with ovarian cancer, including hsa-miR-124-3p, hsa-miR-146a-5p, hsa-miR-30a-5p, EP300, GATA2, and STAT3." (PMID 34539736, 2021). "Considering the potential role of identified molecular signatures in the tumor microenvironment, two biomolecules, GATA2 and TORYAIP1, might be a novel candidate for the treatment in the breast and ovarian cancer." (PMID 33907495, 2021). "A previous study reported a negative correlation between GATA2 and COL1A1 expression in patients with breast and ovarian cancers." (PMID 36360208, 2022).
pulmonary disease (6 papers, 2015 to 2025). "Further research is needed to clarify mechanisms linking GATA2 mutations to lymphoproliferative and pulmonary disorders, improving diagnosis and therapy." (PMID 41438140, 2025). "Transplanting patients with GATA2 deficiency prior to the acquisition of severe infections or secondary organ damage, such as progressive pulmonary disease, is likely to increase long-term survival of adult patients with GATA2 deficiency." (PMID 34244664, 2021).
severe combined immunodeficiency (6 papers, 2019 to 2024). Severe combined immunodeficiency (SCID) comprises a group of rare monogenic primary immunodeficiency disorders characterized by a lack of functional peripheral T lymphocytes resulting in early-onset severe respiratory infections and failure to thrive. "Here, thymic alymphoplasia, immunoglobulin A deficiency, GATA2 deficiency (MonoMac disease) and adenosine deaminase-deficient severe combined immunodeficiency (ADA-SCID) are inherited diseases that have been observed as drivers of secondary PAP." (PMID 33804918, 2021). "PIDs with HPV clinical implications include epidermodysplasia verruciformis (EV), WHIM (warts, hypogammaglobulinemia, infections and myelokathexis) syndrome, DOCK8 mutations, GATA binding protein 2 (GATA2) mutations, and severe combined immunodeficiency (SCID)." (PMID 36960048, 2023). "Underlying diagnoses were IL12RB1 deficiency, NFKB1 haploinsufficiency, IFNGR1 deficiency, GATA2 haploinsufficiency, Kabuki syndrome, NEMO deficiency, and undefined combined immunodeficiency (CID)." (PMID 30984189, 2019).
endometrial cancer (5 papers, 2017 to 2025). Primary or metastatic malignant neoplasm involving the endometrium (mucous membrane that lines the endometrial cavity). "Previously, the essential mediator of the early decidual response HAND2 was identified as a specific target of the GATA2 transcription factor, and hypermethylation of this gene is a common and crucial alteration in endometrial cancer." (PMID 28125717, 2017). "Loss of Gata2 is associated with PGR-independent squamous metaplasia of the endometrial lining coupled to a cancer-like gene expression profile, and reduced GATA2 expression may correlate with aggressive behavior of endometrial carcinomas." (PMID 39443360, 2024). "Recently, GATA2 RNA levels were reported to be reduced in endometrial carcinomas compared with benign endometrium in an analysis that did not stratify by tumor subtype." (PMID 40168074, 2025). "Using cell lines derived from endometrioid (non-USC) endometrial carcinomas, the authors showed that increased GATA2 expression can suppress tumor growth and invasion." (PMID 40168074, 2025).